SNORD33 (small nucleolar RNA, C/D box 33)
Synonyms: U33; RNU33
Gene: Small nucleolar RNA gene on chromosome 19 (49,490,615 to 49,490,699, forward strand). Ensembl gene ENSG00000199631.
Gene Ontology:
Biological process: RNA processing
Cellular component: nucleolus
Homologues: Orthologues: chimpanzee SNORD33 (100% identical), macaque SNORD33 (96% identical), dog SNORD33 (91% identical), guinea pig SNORD33 (87% identical), rabbit SNORD33 (85% identical), mouse Snord33 (84% identical), rat Snord33 (81% identical), pig SNORD33 (78% identical). Paralogues in human: SNORD32A (68% identical), SNORD32B (64% identical), SNORD33 (55% identical).
Diseases named in the same sentence as SNORD33 in open-access papers:
SNORD33 is named in the same sentence as 5 diseases in open-access papers, as found by Europe PMC text mining. Sharing a sentence is not in itself a finding about the gene and the disease. The quoted sentences say what the papers report.
lung cancer (5 papers, 2010 to 2024). A malignant neoplasm involving the lung. "SNORD33 is located in chromosome 19q13.3 that contain potential oncogenes in lung cancer, while SNORD66 and SNORD76 are situated in chromosomal regions 3q27.1 and 1q25.1, respectively." (PMID 20663213, 2010). "Similarly, SNORD78, a snoRNA with functions akin to SNORD33, promotes lung cancer cell growth, thus accelerating lung cancer progression." (PMID 39834830, 2024). "Moreover, snoRD33 is located at chromosome 19q13.3 that contains oncogenes involved in different malignances including lung cancer, whereas snoRD66 and snoRD76 are located at chromosomal regions 3q27.1 and 1q25.1, respectively." (PMID 22613733, 2012). "Furthermore, SNORD33 dysregulation may facilitate cell metastasis and hasten lung cancer progression." (PMID 39834830, 2024). "SNORD33 and SNORD37 are located on chromosome 19q13.3 and 19p13.3, respectively that contain potential oncogenes involved in malignancies, including lung cancer 20,57,58." (PMID 29090068, 2017). "Since there is no single validated molecular biomarker for early lung cancer detection and spectrum of biomarkers is needed for early diagnosis, a panel of biomarkers including miR-223, miR-212, miR-3074, miR-192, SNORD33 and SNORD37 were the candidates in our study." (PMID 29090068, 2017).
non-small cell lung carcinoma (3 papers, 2016 to 2024). A group of at least three distinct histological types of lung cancer, including non-small cell squamous cell carcinoma, adenocarcinoma, and large cell carcinoma. "Also, SNORD33, SNORD66, and SNORD76 are highly expressed in non-small-cell lung cancer (NSCLC) patients’ plasma, serving as sensitive and specific markers for NSCLC, which causes about 25% of cancer-related deaths." (PMID 39000310, 2024). "It has been reported that SNORD33, SNORD66, SNORD76 could be the potential biomarkers for non-small cell lung cancer (NSCLC)." (PMID 33461545, 2021).
gastric cancer (1 paper, 2025). A primary or metastatic malignant neoplasm involving the stomach. "In cultured gastric cancer cell lines (MKN-45, HGC-27, AGS, SNU-1), the expression of SNORA37 and SNORD33 was consistently enhanced than that of GES-1 cells." (PMID 39815331, 2025).
cancer (6 papers, 2010 to 2024). A tumor composed of atypical neoplastic, often pleomorphic cells that invade other tissues. "Dysregulation of SNORD33, whether through overexpression or underexpression, may contribute to cancer or inflammation development." (PMID 39834830, 2024). "In contrast, SNORD33, SNORD66, and SNORD76 exhibited significantly higher expressions in NSCLC patients as compared with healthy controls, suggesting that the elevated expressions of the three genes in plasma might be cancer-associated changes (All P < 0.01)." (PMID 20663213, 2010). "In particular, high expressions of SNORD33 and SNORD76 were only observed in plasma from cancer patients." (PMID 20663213, 2010). "SnoRD33, snoRD66, and snoRD76 were found up-regulated in plasma from NSCLC patients, while snoRD33, snoRD66, snoRD42, and snoRD78 were investigated in sputum samples of patients with the same type of cancer." (PMID 31416190, 2019). "The finding that the increased plasma expressions of SNORD33 and SNORD76 solely occurred in NSCLC patients suggest that these two genes whose upregulations could be cancer-specific changes." (PMID 20663213, 2010). "miR-223, miR-212, miR-192, SNORD33 and SNORD37 did not alter in tissue samples of cancer patients compared to non-cancers." (PMID 29090068, 2017).
SNORD33 also shares sentences with these, for which no sentence is quoted: Tumor (2 papers).